PAK2 (p21 (RAC1) activated kinase 2)
Description:
Serine/threonine protein kinase that plays a role in a variety of different signaling pathways including cytoskeleton regulation, cell motility, cell cycle progression, apoptosis or proliferation. Acts as a downstream effector of the small GTPases CDC42 and RAC1. Activation by the binding of active CDC42 and RAC1 results in a conformational change and a subsequent autophosphorylation on several serine and/or threonine residues. Full-length PAK2 stimulates cell survival and cell growth. Phosphorylates MAPK4 and MAPK6 and activates the downstream target MAPKAPK5, a regulator of F-actin polymerization and cell migration. Phosphorylates JUN and plays an important role in EGF-induced cell proliferation. Phosphorylates many other substrates including histone H4 to promote assembly of H3.3 and H4 into nucleosomes, BAD, ribosomal protein S6, or MBP. Phosphorylates CASP7, thereby preventing its activity. Additionally, associates with ARHGEF7 and GIT1 to perform kinase-independent functions such as spindle orientation control during mitosis. On the other hand, apoptotic stimuli such as DNA damage lead to caspase-mediated cleavage of PAK2, generating PAK-2p34, an active p34 fragment that translocates to the nucleus and promotes cellular apoptosis involving the JNK signaling pathway. Caspase-activated PAK2 phosphorylates MKNK1 and reduces cellular translation.
Synonyms: PAK65; PAKgamma; KNO2
Tractability: Small molecule: a high-quality ligand is known; it belongs to a druggable protein family. Antibody: its Gene Ontology location is reachable by antibodies, with high confidence. PROTAC: UniProt records ubiquitination sites on it; ubiquitination databases record sites on it; its protein half-life has been measured; a small molecule that binds it is known.
Target class: Protein Kinase; STE protein kinase PAKA subfamily; Enzyme; STE protein kinase group; Kinase; STE protein kinase STE20 family
Chemical probes: G-5555 (high quality)
Gene: Protein-coding gene on chromosome 3 (196,739,743 to 196,832,647, forward strand). Ensembl gene ENSG00000180370.
Subcellular location: Cytoplasm (Serine/threonine-protein kinase PAK 2); Nucleus; Nucleus (PAK-2p34); Cytoplasm, perinuclear region; Membrane
Subcellular location (Human Protein Atlas): Nuclear speckles; Nucleoplasm; Cytosol; Focal adhesion sites
Pathways (Reactome):
Signal Transduction: CDC42 GTPase cycle; MAPK6/MAPK4 signaling; RAC1 GTPase cycle; RAC2 GTPase cycle; RAC3 GTPase cycle; RHO GTPases activate PAKs; RHOG GTPase cycle; RHOH GTPase cycle; RHOJ GTPase cycle; RHOQ GTPase cycle; RHOU GTPase cycle; RHOV GTPase cycle; VEGFA-VEGFR2 Pathway; VEGFR2 mediated vascular permeability
Immune System: CD209 (DC-SIGN) signaling; CD28 dependent Vav1 pathway; FCERI mediated MAPK activation; Gene and protein expression by JAK-STAT signaling after Interleukin-12 stimulation; Generation of second messenger molecules
Developmental Biology: Activation of RAC1; Ephrin signaling; Sema3A PAK dependent Axon repulsion
Programmed Cell Death: Regulation of PAK-2p34 activity by PS-GAP/RHG10; Regulation of activated PAK-2p34 by proteasome mediated degradation; Stimulation of the cell death response by PAK-2p34
Disease: Nef and signal transduction
Muscle contraction: Smooth Muscle Contraction
Gene Ontology:
Molecular function: cadherin binding; identical protein binding; protein binding; protein kinase binding; protein serine kinase activity; protein serine/threonine kinase activity; protein tyrosine kinase activator activity; small GTPase binding; protein kinase activity; ATP binding
Biological process: adherens junction assembly; bicellular tight junction assembly; intracellular signal transduction; negative regulation of apoptotic process; negative regulation of stress fiber assembly; positive regulation of extrinsic apoptotic signaling pathway; protein autophosphorylation; protein localization to cell-cell junction; protein phosphorylation; regulation of cytoskeleton organization; cell migration; cellular response to starvation; regulation of axonogenesis; regulation of MAPK cascade; signal transduction; stimulatory C-type lectin receptor signaling pathway; vascular endothelial growth factor receptor signaling pathway; cardiac muscle hypertrophy; cellular response to transforming growth factor beta stimulus; regulation of actin filament organization
Cellular component: cell-cell junction; cytoplasm; cytosol; membrane; nuclear speck; nucleoplasm; nucleus; plasma membrane; glutamatergic synapse; perinuclear region of cytoplasm; postsynaptic density; secretory granule
Genetic constraint (gnomAD): Loss-of-function variants: 1 observed, 7.17 expected, observed/expected ratio (o/e) 0.14, 90% interval 0.049 to 0.66. That is too few expected variants to judge how well the gene tolerates losing a copy. Missense variants: 29 observed, 72.25 expected, observed/expected ratio (o/e) 0.4, 90% interval 0.3 to 0.55. Synonymous variants: 21 observed, 25.16 expected, observed/expected ratio (o/e) 0.83, 90% interval 0.59 to 1.2.
Homologues: Orthologues: macaque PAK2 (99% identical), rabbit PAK2 (98% identical), guinea pig PAK2 (97% identical), mouse Pak2 (97% identical), pig PAK2 (97% identical), rat Pak2 (97% identical), dog PAK2 (93% identical), zebrafish pak2a (86% identical), zebrafish pak2b (86% identical), chimpanzee PAK2 (83% identical), tropical clawed frog pak2 (82% identical), Drosophila melanogaster Pak (65% identical). Paralogues in human: PAK1 (78% identical), PAK3 (77% identical), PAK4 (38% identical), PAK5 (38% identical), PAK6 (36% identical), MAP3K19 (27% identical), MAP3K1 (26% identical), MAP4K3 (24% identical), OXSR1 (24% identical), SLK (24% identical), MAP4K4 (24% identical), MINK1 (24% identical), and 23 more.
Diseases named in the same sentence as PAK2 in open-access papers:
PAK2 is named in the same sentence as 149 diseases in open-access papers, as found by Europe PMC text mining. Sharing a sentence is not in itself a finding about the gene and the disease. The quoted sentences say what the papers report.
breast carcinoma (22 papers, 2014 to 2025). "Aberrant activation of PAK2 has been strongly associated with therapeutic resistance in breast cancer, and its inhibition has been shown to suppress the development of multidrug resistance." (PMID 41423632, 2025). "In clinical observations, PAK2 expression is associated with poor outcomes in patients with estrogen receptor-positive (ER+) breast cancer resistant to endocrine therapy, as it drives estrogen-independent tumor growth." (PMID 39769207, 2024). "Elevated PAK2 activity reportedly interrupts apoptotic responses, causes anchorage-independent survival and growth, and leads to resistance of breast cancer cells to drug-induced apoptosis." (PMID 29362401, 2018). "Elevated PAK2 expression also associated with poor prognosis in breast cancer patients." (PMID 41423632, 2025). "PAK2 overexpression linked to poor prognosis in ER+ breast cancer and TNBC." (PMID 39769207, 2024). "Consistently, our study revealed that FRAX597 significantly inhibited PAK2 phosphorylation and effectively reduced breast cancer cell clustering, invasion, migration, and metastatic spread both in vitro and in vivo." (PMID 41423632, 2025). "Among the identified hub genes, PAK2 was significantly upregulated in breast cancer tissues and cell lines, and its elevated expression was associated with poor patient prognosis." (PMID 41423632, 2025). "Ultimately, therapeutic strategies aimed at reducing CTC cluster formation by targeting key mediators such as PAK2 hold substantial promise for improving outcomes in patients with breast cancer." (PMID 41423632, 2025). "In breast cancer specifically, PAK2 has been reported to modulate apoptosis through caspase-7 phosphorylation." (PMID 41423632, 2025). "Then we performed IF analysis and found that PAK2 and E-cadherin can colocalize in breast cancer cells." (PMID 41423632, 2025). "PAK2 mRNA expression was markedly elevated in breast cancer cell lines compared with normal MCF10A cells, as indicated by the Cancer Cell Line Encyclopedia (CCLE)." (PMID 41423632, 2025). "Collectively, this work reveals new insights into the molecular mechanisms driving CTC cluster formation and highlights PAK2 as a potential prognostic biomarker and therapeutic target for preventing metastasis in patients with breast cancer." (PMID 41423632, 2025). "In preclinical studies, PAK2 inhibition also has shown potent antitumor activity, including suppression of breast cancer cell proliferation, reduced tumor growth in vivo, and inhibition of metastatic phenotypes." (PMID 41423632, 2025). "Compared with control treatment, Cd exposure led to significant increases in H3K79me1 levels and Pak2 transcript levels in mammary tumor tissues." (PMID 40919610, 2025). "As a tumor suppressor, miR-216a-5p targets PAK2 in breast cancer to regulate cell proliferation and metastasis." (PMID 37819496, 2023). "It is also well known that PAK2 is higher in ER+ breast cancer patients and well-correlated with a poor prognosis." (PMID 36830998, 2023). "Current studies have verified that PAK2 is overexpressed in a variety of malignant tumor cells, including lung cancer, gastric cancer, pancreatic cancer, and breast cancer." (PMID 34853631, 2021). "It inhibits the cell proliferation and metastasis by targeting Janus kinase 2 (JAK2)/signal transducer and activator of transcription 3 (STAT3)-mediated EMT process in GC and by targeting p21-activated protein kinase 2 (PAK2) in breast cancer." (PMID 33028884, 2020). "It has been demonstrated that breast cancer cells with low PAK2 activity exhibit strong sensitivity to the anti-cancer drugs cisplatin and taxol." (PMID 30754684, 2019). "PAK2 downregulates caspase 3 to block the generation of PAK2p34 and promotes breast cancer cell survival, leading to MDR." (PMID 30754684, 2019). "Accumulating evidence indicates that PAK2 are either up-regulated or hyperactivated in a variety of human cancers, including ovarian cancer and breast cancer." (PMID 24621074, 2014).
breast carcinoma (continued). "Pak2-depleted breast cancer cells contain significantly larger focal adhesions and are unable to generate new focal adhesions." (PMID 25050916, 2014). "In addition, IHC data from the HPA database revealed that PAK2 was typically undetectable in normal breast tissue, but highly expressed in breast cancer samples." (PMID 41423632, 2025). "In this study, we explored the role of PAK2 in CTC cluster formation in breast cancer." (PMID 41423632, 2025). "Furthermore, high PAK2 expression correlated with significantly poorer DMFS in breast cancer patients." (PMID 41423632, 2025). "Importantly, our study extends this knowledge by establishing a direct link between PAK2 and the formation of breast cancer CTC clusters." (PMID 41423632, 2025). "In breast cancer, PAK2 modulates apoptosis via caspase-7 phosphorylation." (PMID 39769207, 2024). "Increased PAK2 expression in breast cancer cells prevents apoptosis through regulating caspase-7." (PMID 36830998, 2023). "Through phosphoproteomics analysis of lapatinib-sensitive (SKBR3) and lapatinib-resistant (SKBR3-LR) breast cell lines, p21-activated kinase 2 (PAK2) was identified as an effective therapeutic target to overcome acquired lapatinib resistance in HER2-positive breast cancer." (PMID 34095463, 2021). "MiR-23b could regulate cytoskeletal reorganization and contribute to reduced cell motility and invasion via its target PAK2 in breast cancer cell lines." (PMID 34289845, 2021). "Moreover, PAK2 was shown to inhibit chemotherapeutic drug-induced apoptosis by phosphorylating caspase-7 in breast cancer cells." (PMID 29362401, 2018). "A number of human breast cancer lines exhibit constitutively elevated PAK1 and PAK2 activity, in some cases associated with the presence of an activated Rac GTPase and PAK activity has been linked to tumor invasiveness and motility of a variety of human cancer cell lines." (PMID 25050916, 2014). "Together, these findings suggest that PAK2 could serve as a novel target to limit metastasis in breast cancer, and pharmacological PAK2 inhibitors such as FRAX597 could provide multiple therapeutic benefits, including limiting tumor progression, reducing metastasis and improving patient outcomes." (PMID 41423632, 2025). "Interestingly, PAK-1 and PAK-2 appear to play opposing roles in models of breast cancer." (PMID 27535340, 2016). "The biological function of the identified hub gene PAK2 was validated via in vitro CTC cluster formation cell models and in vivo orthotopic in situ breast cancer mouse models." (PMID 41423632, 2025). "In summary, our study identifies PAK2 as a critical regulator of CTC cluster formation and breast cancer metastasis." (PMID 41423632, 2025). "Collectively, these results demonstrate that PAK2 drives CTC cluster formation and regulates malignant behaviors in breast cancer cells." (PMID 41423632, 2025). "This study revealed that PAK2 promotes CTC cluster formation and breast cancer metastasis by enhancing E-cadherin-mediated cell-cell adhesion." (PMID 41423632, 2025). "PAK2 is unique among the PAK family: Activated by Cdc42, full-length PAK2 protects breast cancer cells from drug-induced cell death; when proteolytically cleaved by caspase 3, PAK2 generates its fragment PAK2p34 that favors apoptosis." (PMID 30754684, 2019). "One of the important ways Cdc42 affect Bcl-2 family during breast cancer is by stimulating its downstream effector PAK (both PAK1 and PAK2)." (PMID 30754684, 2019). "Furthermore, the PAK2 inhibitor FRAX597 significantly suppressed both CTC cluster formation and lung metastasis in orthotopic breast cancer mouse models." (PMID 41423632, 2025). "In this study, through integrative transcriptomic analyses of single CTCs and CTC clusters combined with molecular function studies, we explored for the first time the role of PAK2 in facilitating CTC cluster formation and metastatic progression in breast cancer." (PMID 41423632, 2025).
breast carcinoma (continued). "We demonstrate that PAK2 promotes CTC clustering through its kinase activity, which enhances E-cadherin phosphorylation at Ser840 and strengthens cell-cell adhesion, ultimately contributing to breast cancer metastasis." (PMID 41423632, 2025). "Collectively, our data demonstrate that PAK2 inhibition via FRAX597 effectively suppresses CTC cluster formation and metastatic potential, providing strong preclinical support for the targeting of PAK2 in breast cancer therapy." (PMID 41423632, 2025). "Similarly, in luminal breast cancer, IGF1R is up-regulated and promoted antiestrogen resistance by activating PAK2/PIX." (PMID 36359853, 2022). "Another study on breast cancer demonstrates that depletion of CD44 substantially hampers the aggregation of circulating tumor cells (CTCs) which contribute to cell migration, accompanied by down-regulation of p21-activated kinase 2 (PAK2)." (PMID 33303029, 2020). "Furthermore, in orthotopic breast cancer mouse models, systemic administration of FRAX597 not only suppressed primary tumor growth but also markedly diminished the metastatic burden in the lungs, reinforcing the potential clinical utility of PAK2 inhibition." (PMID 41423632, 2025). "By integrating computational docking, IF colocalization, Co-IP assays and functional studies, our study revealed that PAK2 directly interacts with E-cadherin and phosphorylates it at Ser840, thereby strengthening intercellular adhesion and promoting CTC cluster formation in breast cancer." (PMID 41423632, 2025).
gastric cancer (17 papers, 2013 to 2025). A primary or metastatic malignant neoplasm involving the stomach. "Most importantly, PAK2 has become a promising target for cancer prevention and might be associated with advanced tumor progression and poor prognosis in gastric cancer 31-33." (PMID 32483448, 2020). "Our data suggest for the first time that PAK2 activation may be associated with advanced tumor progression and poor prognosis of gastric cancer." (PMID 24621074, 2014). "In conclusion, our data suggest for the first time that the activation of PAK2 may be associated with advanced tumor progression of gastric cancer." (PMID 24621074, 2014). "A study aiming to find a potential correlation between tumor progression and prognosis and PAK2 expression and its phosphorylation state in gastric cancer revealed that the poor prognosis of gastric cancer and accelerated tumor progression may be linked to PAK2 activation." (PMID 39769207, 2024). "In this study, the expression levels of PAK2 and pSer20PAK2 proteins were both significantly higher (both p < 0.001) in gastric cancer tissues compared with normal gastric mucosa." (PMID 39769207, 2024). "The potential of CDK12/PAK2 as a therapeutic target for patients with gastric cancer was highlighted in a previous study." (PMID 37260411, 2023). "Gastric cancer: PAK2 lies in the downstream of Rho GDP dissociation inhibitor 2 (RhoGDI2) signaling." (PMID 36830998, 2023). "Cathepsin D and PAK2 are regulated by RhoGDI2 in mediating the chemoresistance in gastric cancer cells." (PMID 36830998, 2023). "CDK12 directly binds to and phosphorylates PAK2 at Thr134/Thr169 to activate the MAPK signaling pathway in gastric cancer." (PMID 36230657, 2022). "Our results showed that the T134/T169 phosphorylated by CDK12 is important for the function of PAK2 in human gastric cancer." (PMID 32483448, 2020). "Then, we examined the co-localization of CDK12 and PAK2 by laser scanning confocal microscope which revealed that they co-localized in the nuclear and cytoplasm in gastric cancer cells." (PMID 32483448, 2020). "Higher level of PAK2 and pSer20PAK2 was significantly correlated with poor disease prognosis and unfavorable clinicopathologic features in gastric cancer." (PMID 31587474, 2019). "Expression patterns and subcellular localizations of PAK2 and Ser20-phosphorylated PAK2 (pSer20PAK2) in 82 gastric cancer patients were detected by immunohistochemistry." (PMID 24621074, 2014). "Expression patterns and subcellular localizations of PAK2 and pSer20PAK2 in gastric cancer and normal gastric mucosa were detected by immunohistochemistry." (PMID 24621074, 2014). "In line with these previous findings, our data showed the upregulation of PAK2 and pSer20PAK2 in gastric cancer tissues, implying the activation of PAK2 in tumorigenesis of this disease." (PMID 24621074, 2014). "The overexpression of PAK2 and pSer20PAK2 proteins were both identified as independent prognostic factors in gastric cancer." (PMID 24621074, 2014). "Of 82 patients with gastric cancer, 62 (75.61%) and 69 (84.15%) were highly expressed PAK2 and pSer20PAK2, respectively." (PMID 24621074, 2014). "Both PAK2 and pSer20PAK2 immunostainings were localized in the cytoplasm of tumor cells of gastric cancer tissues." (PMID 24621074, 2014). "More interestingly, the aberrant expressions of PAK2 and pSer20PAK2 proteins were both independent prognostic factors for gastric cancer." (PMID 24621074, 2014). "In the current study, we demonstrated that the expression levels of PAK2 and pSer20PAK2 proteins were significantly higher in gastric cancer than in normal gastric mucosa." (PMID 24621074, 2014). "PAK2 plays roles in RhoGDI2-mediated chemoresistance in gastric cancer." (PMID 36230657, 2022). "For miR-511-5p, it can impede the migration and invasion of gastric cancer via targeting PAK2." (PMID 35186236, 2022). "These phosphorylation sites of PAK2 may act as prognostic markers for gastric cancer cell proliferation and tumor growth." (PMID 32483448, 2020).